ASAH2 (N-acylsphingosine amidohydrolase 2)
Description:
Plasma membrane ceramidase that hydrolyzes sphingolipid ceramides into sphingosine and free fatty acids at neutral pH. Ceramides, sphingosine, and its phosphorylated form sphingosine-1-phosphate are bioactive lipids that mediate cellular signaling pathways regulating several biological processes including cell proliferation, apoptosis and differentiation. Also catalyzes the reverse reaction allowing the synthesis of ceramides from fatty acids and sphingosine. Together with sphingomyelinase, participates in the production of sphingosine and sphingosine-1-phosphate from the degradation of sphingomyelin, a sphingolipid enriched in the plasma membrane of cells. Also participates in the hydrolysis of ceramides from the extracellular milieu allowing the production of sphingosine-1-phosphate inside and outside cells (By similarity). This is the case for instance with the digestion of dietary sphingolipids in the intestinal tract (By similarity).
Synonyms: N-CDase; NCDase; HNAC1; BCDase; LCDase
Tractability: Antibody: UniProt places it where antibodies can reach, with high confidence; its Gene Ontology location is reachable by antibodies, with high confidence; UniProt predicts a signal peptide or a membrane-spanning region. PROTAC: UniProt records ubiquitination sites on it; ubiquitination databases record sites on it; a small molecule that binds it is known.
Target class: Enzyme; Hydrolase
Gene: Protein-coding gene on chromosome 10 (50,182,778 to 50,279,720, reverse strand). Ensembl gene ENSG00000188611.
Subcellular location: Cell membrane (Neutral ceramidase); Membrane raft; Membrane, caveola; Golgi apparatus membrane; Mitochondrion; Secreted, extracellular exosome; Secreted (Neutral ceramidase soluble form)
Subcellular location (Human Protein Atlas): Focal adhesion sites
Pathways (Reactome):
Metabolism: Glycosphingolipid catabolism
Gene Ontology:
Molecular function: calcium ion binding; N-acylsphingosine amidohydrolase activity; zinc ion binding
Biological process: cellular response to cytokine stimulus; ceramide biosynthetic process; ceramide catabolic process; ceramide metabolic process; negative regulation of apoptotic signaling pathway; regulation of mitotic cell cycle; sphingosine biosynthetic process; sphingosine metabolic process; lipid digestion; long-chain fatty acid biosynthetic process; sphingolipid metabolic process
Cellular component: extracellular exosome; Golgi apparatus; Golgi membrane; mitochondrion; plasma membrane; caveola; extracellular region; membrane raft; cytoplasm
Genetic constraint (gnomAD): Loss-of-function variants: 47 observed, 71.54 expected, observed/expected ratio (o/e) 0.66, 90% interval 0.52 to 0.84. The upper end of that interval is the gene's LOEUF score, 0.84, which puts it in group 3 of 6, group 1 being the genes least tolerant of losing a copy. Missense variants: 684 observed, 766.08 expected, observed/expected ratio (o/e) 0.89, 90% interval 0.84 to 0.95. Synonymous variants: 254 observed, 270.05 expected, observed/expected ratio (o/e) 0.94, 90% interval 0.85 to 1.04.
Homologues: Orthologues: macaque ASAH2 (96% identical), dog ASAH2 (85% identical), mouse Asah2 (79% identical), rat Asah2 (78% identical), zebrafish asah2 (56% identical), tropical clawed frog asah2 (55% identical), Drosophila melanogaster CDase (39% identical). Paralogues in human: ASAH2B (20% identical).
Diseases named in the same sentence as ASAH2 in open-access papers:
ASAH2 is named in the same sentence as 50 diseases in open-access papers, as found by Europe PMC text mining. Sharing a sentence is not in itself a finding about the gene and the disease. The quoted sentences say what the papers report.
colon carcinoma (12 papers, 2019 to 2025). "The molecular and pharmacological inhibition of the neutral ceramidase, encoded by ASAH2, increased ceramide levels accompanied by decreased cell survival and increased apoptosis in colon cancer cells." (PMID 33716775, 2021). "In colon cancer, targeting ASAH2 on MDSCs infiltrating tumors with NC06 has been shown to induce ferroptosis in these cells, thereby reducing their presence in tumor cells." (PMID 39867656, 2024). "Given that the ASAH2 plays an important role in positively regulating the MDSC, and ASAH2 was found highly expressed in tumor-infiltrating MDSCs in colon carcinoma." (PMID 36926345, 2023). "N-acylsphingosine amidohydrolase (ASAH2), a kind of neutral ceramidase, is highly expressed in tumor-infiltrating MDSCs (myeloid-derived suppressor cells) of colon cancer." (PMID 35884370, 2022). "Inhibition of ASAH2 leads to an increase of Cer, which is accompanied with activation of apoptosis and autophagy, and a decreased survival of colon cancer cells, whereas its inhibition exerts only minimal effects in non-tumor intestinal cells." (PMID 31801289, 2019). "Similar to that, neutral ceramidase (ASAH2) has been identified as an important regulator of cell survival in several colon cancer cell lines." (PMID 31801289, 2019). "Additionally, ASAH2 inhibition induced delayed tumor growth in a xenograft model with an increased ceramide level and decreased proliferation, which confirmed the role of neutral ceramidase in the regulation and development of colon cancer." (PMID 31817238, 2019). "Sakamoto and coworkers found expressed ASAH2 in colon cancer cells." (PMID 31817238, 2019). "Thus, this explains the role of ASAH2 in regulating the basal activation of AKT, and therefore ASAH2 can be proposed as a novel target for colon cancer therapy." (PMID 31817238, 2019). "Inhibition of ASAH2 decreased active (phosphorylated) AKT pool and induced dephosphorylation of GSK3β, which was then followed by phosphorylation and degradation of β-catenin and suppression of proliferation of colon cancer cells, both in vitro and in vivo." (PMID 31801289, 2019).
Alzheimer disease (4 papers, 2019 to 2025). A progressive, neurodegenerative disease characterized by loss of function and death of nerve cells in several areas of the brain leading to loss of cognitive function such as memory and language. "In the case of Asah2 deficiency, its protective role against ER stress and nutrient-deprivation-induced necroptosis via autophagy was already mentioned, and a similar downregulation was also observed for Alzheimer’s disease." (PMID 31766565, 2019). "Neurodegenerative diseases occur more frequently in patients with inflammatory gastrointestinal diseases including IBD or CeD, while ASAH2 has been discovered in Parkinson’s disease and Alzheimer’s disease." (PMID 36118884, 2022). "We found that neutral ceramidase (ASAH2/ASAH2B) and sortilin-related VPS10 domain-containing receptor 2 (SORCS2) were significantly elevated in the serum of individuals who later developed Alzheimer's dementia." (PMID 40772191, 2025).
colitis (3 papers, 2016 to 2025). Inflammation of the colon. "Here, a protective mechanism by which IEC NcDase deficiency (Asah2ΔIEC) and its-related gangliosides prevent dextran sulfate sodium (DSS)-induced colitis in mice is described." (PMID 41201002, 2025).
glioma (3 papers, 2020 to 2022). A benign or malignant brain and spinal cord tumor that arises from glial cells (astrocytes, oligodendrocytes, ependymal cells). "Meanwhile, neutral ceramidase isoforms (i.e., ASAH2/ASAH2B) are associated with a better prognosis and are elevated in IDHmut glioma subtypes." (PMID 36012521, 2022). "Patients’ samples with IDHmut consistently displayed significantly higher mRNA levels of SMPD3 and ASAH2 along with related genes in both lower grade glioma as well as high grade gliomas." (PMID 33050528, 2020). "Overall, Western blot analysis confirmed upregulation of key sphingolipid enzymes such as SMPD3 and ASAH2, in IDH1mut glioma cells specifically, which suggested that the pathway is upregulated towards the elevating the availability of sphingosine and ceramide." (PMID 33050528, 2020). "In contrast, there was no signficant correlation of elevated expression of other ceremidases (ASAH2, ACER2, ACER3) with poor glioma patient outcomes." (PMID 35741006, 2022). "We also compared the mRNA levels for SMPD3, ASAH2 and other sphingolipid genes available through the TCGA database between IDHmut (n = 218) and IDHWT (n = 68) from lower grade glioma and higher-grade glioblastomas." (PMID 33050528, 2020).
Obesity (3 papers, 2022 to 2024). Accumulation of substantial excess body fat. "Furthermore, obesity induced by a high-fat feeding provoked a crucial decrease in ASAH2 expression (−12.19%, p < 0.05, vs. control group), which was further elevated by prolonged CBD treatment (+20.03%, p < 0.05) in comparison to the rats from the HFD group." (PMID 35216351, 2022).
colorectal cancer (2 papers, 2019 to 2024). A primary or metastatic malignant neoplasm that affects the colon or rectum. "ASAH2, which is highly expressed in the small intestine along the brush border, plays an essential role in the pathogenesis of colorectal cancer." (PMID 31817238, 2019). "This came to light through the overexpression of AKT (constitutively active AKT-DD, phospho-mimic), which leads this mutant to overcome the growth-suppressive effects of ASAH2 inhibition in colorectal cancer (CRC) cells." (PMID 31817238, 2019).
glaucoma (2 papers, 2019 to 2024). Increased pressure in the eyeball due to obstruction of the outflow of aqueous humor. "We found significant differences in glucosylsphingosine lipids, consistent with decreased GBA and GBA2 and increased ASAH1 and ASAH2 immunoreactivity in glaucoma, suggesting the potential impairment of sphingolipid enzymatic pathways in lysosomal and nonlysosomal cellular compartments." (PMID 31022733, 2019). "In GAPDH normalized Western blots, we found elevated ASAH1 and ASAH2 levels in glaucoma." (PMID 31022733, 2019).
type 2 diabetes (2 papers, 2019 to 2024). "In our previous study using a genetic model of type 2 diabetes (the db/db mouse), we assessed potential effects on genes linked to cardiotoxicity genes (Kcnk1, Asah2, B4glant, MMP-3), and reported no adverse effects after ENOblock treatment." (PMID 30679508, 2019).
astrocytoma (1 paper, 2020). "Overall, certain sphingolipid genes (e.g., SMPD3 and ASAH2) follow a similar pattern; their mRNA levels are very high in oligodendroglioma, followed by astrocytoma, and finally the lowest in glioblastomas." (PMID 33050528, 2020). "Indeed, a comparison of SMPD3 and ASAH2 proteins levels in these cell lines show an upregulation of the sphingolipid degradation pathway in both oligodendroglioma as well as astrocytoma." (PMID 33050528, 2020). "Interestingly, the astrocytoma cell line available to us (BT142) presented higher expression of SMPD3 and ASAH2 compared with the oligodendroglioma." (PMID 33050528, 2020).
atherosclerosis (1 paper, 2023). A disease characterized by the build-up of fatty material and calcium deposition in the arterial wall resulting in partial or complete occlusion of the arterial lumen. "We are not aware of any genetic association between ASAH2 and atherosclerosis." (PMID 37944753, 2023). "Alternatively, ASAH2 could affect atherosclerosis through its effects on sphingolipids, independent of its effect on HDL, through their effects on inflammatory pathways." (PMID 37944753, 2023).
Cerebellar atrophy (1 paper, 2026). Cerebellar atrophy is defined as a cerebellum with initially normal structures, in a posterior fossa with normal size, which displays enlarged fissures (interfolial spaces) in comparison to the foliae secondary to loss of tissue. "Our findings support ASAH2 as a candidate gene for a previously uncharacterized neurodevelopmental disorder with neuropathic features and progressive cerebellar atrophy, underscoring the important role of this ceramidase in human nervous systems." (PMID 41808410, 2026).
Cognitive impairment (1 paper, 2026). Abnormal cognition is characterized by deficits in thinking, reasoning, or remembering. "Here, we report the identification of biallelic ASAH2 variants in an individual with a neurodevelopmental condition featuring cognitive impairment, neuropathy, ophthalmoplegia, and progressive cerebellar and extraocular muscles atrophy." (PMID 41808410, 2026).
Hepatic steatosis (1 paper, 2019). Steatosis is a term used to denote lipid accumulation within hepatocytes. "Although ASAH2 may improve insulin sensitivity and hepatic steatosis and inhibits TNF-α-induced vascular inflammation, only a few studies have targeted the manipulation of ASAH2 expression as a therapeutic approach, as ASAH2 distribution and its functions remain unclear in many respects." (PMID 31817238, 2019).
hepatoblastoma (1 paper, 2025). Hepatoblastoma (HB) is a malignant hepatic tumor and is the most common pediatric liver cancer. "Human serums and hepatoblastoma cells (also referred to as HepG2 cells) were stained and quantified with ASAH2, membrane, and vesicle trafficking proteins." (PMID 40772191, 2025).
liver dysfunction (1 paper, 2025). "The liver was chosen given high levels of ASAH2 expression and prior strong linkage of AD with liver dysfunction." (PMID 40772191, 2025).
nonalcoholic fatty liver disease (1 paper, 2023). "Deletion of Asah2 alleviates diet-induced nonalcoholic steatohepatitis/nonalcoholic fatty liver disease via downregulation of stearoyl-CoA desaturase (Scd1) and reduces cholesterol accumulation." (PMID 37944753, 2023).
tumor (14 papers, 2019 to 2025). "Meanwhile, inhibiting tumor-intrinsic β5-integrin and ASAH2 activities drastically enhanced their susceptibility to gemcitabine and fluorouracil-induced canonical pyroptosis." (PMID 41041050, 2025). "We found that NcDase (ASAH2) expression negatively correlates with the abundance of tumor-infiltrating macrophages and the exhaustion of CD8+ T cells." (PMID 38302493, 2024). "Studies with ASAH2 knockdown (ASAH2-/-) mice demonstrated that deletion of ASAH2 inhibited cell and tumor growth, both in vitro and in vivo, through the WNT/β-catenin, ERK, GSK-3β and Akt pathways." (PMID 34357010, 2021). "This may partially explain why knocking out SEMA6B, MT1E, S100A4, or ASAH2 may significantly promote tumor colony growth." (PMID 39605490, 2024). "Accumulating evidence suggested that the tumor-infiltrating MDSCs are resistant to ferroptosis-mediated cell death because the system Xc- and the neutral ceramidase N-acylsphingosine amidohydrolase (ASAH2) are highly expressed in MDSCs." (PMID 36926345, 2023). "Therefore, targeting ASAH2 with NC06 to induce MDSC ferroptosis may be a potentially effective approach to tumor immunotherapy." (PMID 36317423, 2022). "Targeting ASAH2 induces ferroptosis of MDSCs, reduces MDSC accumulation, increases the activation of tumor-infiltrating cytotoxic T lymphocytes (CTLs), and inhibits tumor growth." (PMID 39262952, 2024). "NC06 is a selective ASAH2 small molecule inhibitor that specifically targets immunosuppressive MDSCs in the tumor microenvironment, inducing ferroptosis in them without directly causing ferroptosis in tumor cells." (PMID 41154692, 2025). "As an inhibitor of ASAH2, NC06 can reduce GSH synthesis and increase lipid ROS to activate ferroptosis in bone marrow mesenchymal stem cells and promote the activation of tumor‐infiltrating cytotoxic T lymphocyte (CTL) to inhibit tumor growth in vivo." (PMID 36317423, 2022).
cancer (7 papers, 2016 to 2024). A tumor composed of atypical neoplastic, often pleomorphic cells that invade other tissues. "The use of the Asah2 inhibitor NC06 to target ASAH2 to induce MDSC ferroptosis is a potentially effective therapy for inhibiting the MDSC accumulation in cancer immunotherapy." (PMID 39192972, 2024).
neurodegenerative disease (6 papers, 2019 to 2025). A disorder of the central nervous system characterized by gradual and progressive loss of neural tissue and neurologic function. "Dysregulation of ASAH2 has been implicated in neurodegenerative diseases, including AD, Parkinson’s disease, and Huntington’s disease." (PMID 40772191, 2025). "Among different molecular targets, N-acylsphingosine amidohydrolase 2 (ASAH2), a key enzyme in ceramide metabolism, has been linked to many neurodegenerative diseases, including AD." (PMID 40772191, 2025). "Clarifying the role of ASAH2 in human diseases and determining its potential for use in the treatment of metabolic disorders and neurodegenerative diseases are critical." (PMID 35283765, 2022). "In summary, finding a suitable animal model and gaining a better understanding of ASAH2 will be of critical importance for clarifying its role in human diseases and in terms of its potential use in the treatment of metabolic disorders and neurodegenerative diseases." (PMID 31817238, 2019).
infection (4 papers, 2017 to 2022). The state of being infected such as from the introduction of a foreign agent such as serum, vaccine, antigenic substance or organism. "Our qRT-PCR data revealed that sphingolipid metabolic key genes encoding enzymes: Cers2, Gba2, Gla, Asah1, Asah2, Acer2, Acer3, Neu3, Sgpp1, and Sphk1 were robustly upregulated in mRNA levels by the infection of C. sinensis." (PMID 36339341, 2022).
cardiovascular disease (1 paper, 2023). "Due to associations of ceramides with cardiovascular disease, we sought to investigate Asah2, which encodes a ceramide-catabolizing neutral ceramidase, as a causal gene for HDL-2b lipoproteins." (PMID 37944753, 2023).
ASAH2 also shares sentences with these, for which no sentence is quoted: brain injury (2 papers); coronary artery disease (2); diabetes (2); metabolic disorders (2); Anxiety (1); breast carcinoma (1); Breast invasive carcinoma (1); breast tumors (1); Farber disease (1); glioblastoma (1); Huntington disease (1); Hypertension (1); Insulin resistance (1); intestinal cancer (1); lung carcinoma (1); melanoma (1); neurodevelopmental disorder (1); neurological disorder (1); neuropathy (1); non-small cell lung carcinoma (1); nonalcoholic steatohepatitis (1); oligodendroglioma (1); Parkinson disease (1); prion disease (1); pulmonary fibrosis (1); renal fibrosis (1); schizophrenia (1); small cell lung carcinoma (1); spinocerebellar ataxia (1).